LRFN1 (leucine rich repeat and fibronectin type III domain containing 1)
Description:
Promotes neurite outgrowth in hippocampal neurons. Involved in the regulation and maintenance of excitatory synapses. Induces the clustering of excitatory postsynaptic proteins, including DLG4, DLGAP1, GRIA1 and GRIN1 (By similarity).
Synonyms: KIAA1484; SALM2
Tractability: Antibody: its Gene Ontology location is reachable by antibodies, with high confidence; UniProt predicts a signal peptide or a membrane-spanning region. PROTAC: ubiquitination databases record sites on it; its protein half-life has been measured.
Gene: Protein-coding gene on chromosome 19 (39,306,566 to 39,320,966, reverse strand). Ensembl gene ENSG00000128011.
Subcellular location: Membrane; Synapse; Postsynaptic density membrane
Pathways (Reactome):
Neuronal System: Synaptic adhesion-like molecules
Gene Ontology:
Molecular function: protein binding
Biological process: regulation of postsynaptic density assembly
Cellular component: plasma membrane; postsynaptic density membrane; cell surface; membrane; synapse
Genetic constraint (gnomAD): Loss-of-function variants: 21 observed, 26.88 expected, observed/expected ratio (o/e) 0.78, 90% interval 0.55 to 1.12. The upper end of that interval is the gene's LOEUF score, 1.12, which puts it in group 4 of 6, group 1 being the genes least tolerant of losing a copy. Missense variants: 912 observed, 1,008.6 expected, observed/expected ratio (o/e) 0.9, 90% interval 0.86 to 0.95. Synonymous variants: 514 observed, 477.24 expected, observed/expected ratio (o/e) 1.08, 90% interval 1 to 1.16.
Homologues: Orthologues: chimpanzee LRFN1 (99% identical), macaque LRFN1 (97% identical), dog LRFN1 (96% identical), pig LRFN1 (96% identical), mouse Lrfn1 (95% identical), rat Lrfn1 (95% identical), guinea pig LRFN1 (94% identical), rabbit LRFN1 (83% identical), tropical clawed frog lrfn1 (59% identical), zebrafish lrfn1 (45% identical). Paralogues in human: LRFN2 (46% identical), LRFN5 (46% identical), LRFN3 (44% identical), LRFN4 (41% identical), SLIT3 (21% identical), SLIT2 (19% identical), LRRN2 (18% identical), SLIT1 (18% identical), LRRN1 (17% identical), LINGO2 (17% identical), LINGO1 (16% identical), LRRN3 (16% identical), and 13 more.
Diseases named in the same sentence as LRFN1 in open-access papers:
LRFN1 is named in the same sentence as 15 diseases in open-access papers, as found by Europe PMC text mining. Sharing a sentence is not in itself a finding about the gene and the disease. The quoted sentences say what the papers report.
breast carcinoma (1 paper, 2021). "The rest of the genes above were also over-expressed metastatic cancers originating from breast cancer (ABCC5), kidney renal clear carcinoma (LRFN1), hepatocellular carcinoma (ELOVL6), and uveal melanoma (HTR2B)." (PMID 34680307, 2021).
lymph node metastasis (1 paper, 2022). "Furthermore, expression of LRFN1 was significantly higher in BCa samples with nodal metastasis compared with those without lymph node metastasis (P < 0.05)." (PMID 35799072, 2022).
pancreatic cancer (1 paper, 2019). "Some studies showed that SALM1/LRFN2 was involved in erythropoiesis and that SALM2/LRFN1 participates in pancreatic cancer cell survival." (PMID 31089399, 2019).
prostate carcinoma (1 paper, 2022). A carcinoma that arises from epithelial cells of the prostate gland. "As for LRFN1, a number of LRFN1-based prognostic models have been shown to be effective in a variety of cancers, including prostate cancer, kidney renal clear cell carcinoma, and OC." (PMID 36003381, 2022).
cancer (3 papers, 2021 to 2022). A tumor composed of atypical neoplastic, often pleomorphic cells that invade other tissues. "In TCGA cohort, increased LRFN1 expression also significantly correlated with high tumor grade and individual clinical cancer stage (P < 0.001)." (PMID 35799072, 2022). "Elevated expression of genes such as ABCC5, LRFN1, ELOVL6, and HTR2B have been associated with metastasis in other cancer types." (PMID 34680307, 2021).
tumor (3 papers, 2022 to 2025). "Our data revealed the tumor-specific and immunological role of miR-187-3p/LRFN1 axis, and highlighted the reprogram of TME and potential clinical applications in ccRCC." (PMID 35799072, 2022). "In conclusion, this study revealed the tumor-specific and immunological role of miR-187-3p/LRFN1 axis in the progression and reshaping of tumor immune microenvironment of ccRCC." (PMID 35799072, 2022). "In this study, we hypothesized that miR-187-3p may play a role in suppressing tumors, and mediates malignancy and tumor immune microenvironment (TIME) by targeting Leucine Rich Repeat and Fibronectin Type III Domain Containing 1 (LRFN1)." (PMID 35799072, 2022).
LRFN1 also shares sentences with these, for which no sentence is quoted: brain tumors (1 paper); clear cell renal cell carcinoma (1); epilepsy (1); hepatocellular carcinoma (1); hyperlipidemia (1); metastatic cancers (1); Obesity (1); retinoblastoma (1); uveal melanoma (1).